ISG15 (ISG15 ubiquitin like modifier)
Diseases named in the same sentence as ISG15 in open-access papers (continued):
Sharing a sentence is not in itself a finding about the gene and the disease.
lung carcinoma (continued). "Interestingly, the levels of not only SIRT1 but also ISG15 and protein ISGylation conjugates were elevated in six of the lung cancer tissues (54.5%), suggesting the involvement of ISG15 and SIRT1 in lung cancer development." (PMID 38443596, 2024). "Therefore, we investigated the expression of PD-L1, ICAM-1, CXCL10, and IFNs-mediated ISG15 expression in patients with lung cancer (LUAD), liver cancer (LIHC), and colorectal cancer (COAD) using the available GEPIA based on the TCGA database." (PMID 38953994, 2024). "This included ISG15, a ubiquitin‐like protein serving as a type of lung cancer tumour suppressor and PML, a key component of PML nuclear bodies (PML‐NBs), which plays the role of a tumour suppressor by contributing to apoptotic induction, inhibiting angiogenesis as well as cell cycle progression." (PMID 36579897, 2023). "ISG15 inhibited lung cancer cell growth by promoting its ubiquitin E3 ligase activity." (PMID 35884544, 2022). "Immunotherapy cohort analysis demonstrated that tumors with high ISG15 expression responded favorably to PD-L1 inhibitors but exhibited resistance to CTLA-4 blockade, findings further validated in lung cancer patients receiving anti-PD-1 therapy." (PMID 40208307, 2025). "Tumors from high ISG15 expressing lung cancer cells such as H1975 and H358 are more sensitive to topotecan and CPT while those expressing low ISG15 such as A549 are less sensitive to these drugs." (PMID 33860729, 2021). "In the search for novel targets of ISGylation in lung cancer, RPPAs uncovered PTEN as a previously unrecognized candidate ISG15 substrate." (PMID 27980214, 2017). "Therefore, IRF1 and STAT1 were knockdown in lung cancer A549 cells, which decreased 20 ng/mL of IFNα/γ-mediated gene expression, including IRF1, STAT1, PD-L1, CXCL10, and ISG15." (PMID 38953994, 2024). "Prompted by our findings that SIRT1 ISGylation is important for tumor progression and the therapeutic response in lung cancer, we analyzed the protein expression levels of SIRT1 and ISG15 in eleven pairs of primary lung adenocarcinoma tissues and adjacent normal tissues." (PMID 38443596, 2024). "In contrast, inhalation delivery of topotecan dramatically reduced the orthotopic growth of all three lung cancer types regardless of high or low ISG15 expression." (PMID 33860729, 2021). "Indeed, engineered overexpression of ISG15 decreased PTEN levels in both murine and human lung cancer cell lines by at least ~40-50% as compared to vector control transfected cells." (PMID 27980214, 2017). "Subcutaneous xenografts derived from the two high ISG15 expressing lung cancer cell lines (H1975 and H358) showed higher sensitivity to inhaled and to a lesser extent IV topotecan compared to the moderate or no response seen in the low ISG15 expressing A549-derived tumors." (PMID 33860729, 2021).
cervical cancer (15 papers, 2015 to 2025). A primary or metastatic malignant neoplasm involving the cervix. "UBE2L6 enhances the binding of ISG15 to cellular proteins and promotes apoptosis in cervical cancer cells." (PMID 40990020, 2025). "In cervical cancer, ISG15 expression was up-regulated and knockdown ISG15 inhibited proliferation and invasion of cervical cancer cell." (PMID 37601683, 2023). "Among the four protective genes, UBE2L6 gene, encoding the ISG15 (IFN‐stimulated gene 15)‐conjugating enzyme UbcH8, was found to be correlated with apoptosis of cervical cancer." (PMID 32902917, 2020). "ISG15 and ISGylated proteins usually act as tumor suppressors in several types of human cancer cell lines, including breast, lung, blood, and cervical cancer cells, and myelogenous leukemia cells." (PMID 29367604, 2018). "Therefore, the role of ISG15 in HPV+ cervical cancer, and other HPV+ cancers, is unclear and requires further investigation." (PMID 40011575, 2025). "The high expressions of ISG15, IFI27, and OASL were also correlated with complete remission in patients with cervical cancer treated with cisplatin." (PMID 37174688, 2023). "Further studies demonstrated that ectopic ISG15 and USP18 inhibited proliferation of myeloma, leukemia and cervical cancer cells." (PMID 27659523, 2016). "Since KU55933 induced the expressions of ISG15, IFI27, and OASL in CDDP-R cancer cells, the effects of the three ISGs on the response to cisplatin therapy were examined in patients with cervical cancer from the TCGA cohort." (PMID 37174688, 2023). "This study also found that high expressions of ISG15, IFI27, and OASL were associated with complete remission in patients with cervical cancer treated with cisplatin but not in those without cisplatin-based therapy." (PMID 37174688, 2023). "However, the role of ISG15 in HPV+ cervical cancer progression is not clear; one study demonstrated that ISG15 depletion reduces proliferation in HPV+ cervical cancer cells, whilst another demonstrated that ISG15 over-expression reduces HPV+ cervical cancer cells growth in vivo." (PMID 40011575, 2025).
HCMV infection (15 papers, 2016 to 2025). "These two observations combine to definitively demonstrate that the upregulation of ISG15 caused by HCMV infection can occur in an IFN-independent, IRF3-dependent manner." (PMID 30871003, 2019). "The induction of ISGs Mx1 and ISG15 was markedly enhanced following HCMV infection of HFF ko-SQSTM1 cells compared to controls." (PMID 39339916, 2024). "Although it is well established that ISG15 and the ISGylation cascade enzymes are induced by cytomegalovirus infection, their role and direct interaction with viral proteins were only recently described." (PMID 34207696, 2021). "Literature suggests that several ISGs, including MX1 and ISG15, have been found to upregulated after human cytomegalovirus (HCMV) infection and behave in an interferon-independent, IRF3-dependent manner." (PMID 33419081, 2021). "In primary HFs significant upregulation of ISG15 transcript was observed following HCMV infection even in the presence of IFNβ blocking antibodies." (PMID 30871003, 2019). "ISG15 protein regulation mirrored that of its transcript with IFNβ neutralization failing to completely inhibit ISG15 expression post HCMV infection." (PMID 30871003, 2019). "During HCMV infection accumulation of both free and conjugated ISG15 can be partially inhibited by interfering with the canonical IFNAR signaling pathway with a JAK inhibitor but some IFN-independent, IRF3-dependent expression remains." (PMID 31921100, 2019). "Several ISGs, including IFIT1, IFIT2, IFIT3, Mx1, Mx2, CXCL10 and ISG15 were found to be upregulated transcriptionally following HCMV infection independently of type I IFN-initiated JAK-STAT signaling, but dependent on intact IRF3 signaling." (PMID 30871003, 2019). "We found that the knockdown of CD147 expression in HFF cells decreased the activation of IFNB1 and interferon-stimulated ISG15 gene expression induced by HCMV infection, as well as expression of the NF-κB downstream genes IL-6 and TNF-α." (PMID 29194430, 2017). "Collectively, these results comparing HCMV and UV-HCMV infection demonstrate that ISG15 expression and protein ISGylation are initially induced by HCMV infection, but are subsequently suppressed in a manner dependent on viral gene expression." (PMID 27564865, 2016). "compare lanes 3–5 and 13–15), indicating that IE1 is required for the suppression of ISG15 expression and ISGylation during HCMV infection." (PMID 27564865, 2016). "In this study we demonstrate that ISGylation suppresses human cytomegalovirus (HCMV) infection but the virus is armed with countermeasures that consecutively reduce ISG15 transcription and protein ISGylation." (PMID 27564865, 2016). "We also found that the levels of ISG15 in uninfected neighboring cells were higher in HCMV infection than in UV-HCMV infection." (PMID 27564865, 2016). "In this study, we show that ISG15 expression and ISGylation are initially induced after HCMV infection but later suppressed by viral responses, and that IE1, a viral inhibitor of STAT signaling, plays an important role in reducing ISG15 transcription." (PMID 27564865, 2016). "The time course of ISG15 expression and protein ISGylation during HCMV infection were investigated with different multiplicity of infections (MOIs)." (PMID 27564865, 2016). "ISG15 transcription is induced in HCMV infection; however, its regulation during infection, the role of ISGylation in viral growth, and viral targets of ISG15 have not been characterized." (PMID 27564865, 2016). "In UV-HCMV infection, the levels of ISG15 and ISG15 conjugates were elevated at 24 and 48 h and correlated proportionally with MOI (lanes 7–11 and 18–22)." (PMID 27564865, 2016). "Other anti-viral candidates not described yet in the context of HCMV infection include the broadly anti-viral ISG15 interactor RNF21341 and TNFSF10, which encodes the NK cell-activating protein TRAIL42,43." (PMID 38409141, 2024). "PARP-1 depletion also elevated IFN-β and ISG15 transcription upon HCMV infection." (PMID 36146855, 2022).
HCMV infection (continued). "It adds complexity to recent work describing ISG15 as an antiviral effector during HCMV infection that is antagonized by IE1, pUL50, pUL26 and pUL25, and potentially explains the persistence of ISG15 even in cells treated with high concentrations of the JAK inhibitor pyridone-6." (PMID 30871003, 2019). "This demonstrates firstly, that nPro/HFs are capable of upregulating ISG15 transcript and secondly that there is a soluble factor produced during HCMV infection that can induce ISG15 upregulation in a STAT1-dependent, IRF3-independent manner, most likely type I IFN." (PMID 30871003, 2019). "Taken together these data demonstrate that whilst soluble IFNβ is a potent driver of STAT-1-dependent ISG15 upregulation during HCMV infection, there is a significant component of ISG15 expression mediated by a type-I IFN signaling-independent, IRF3-dependent mechanism." (PMID 30871003, 2019). "ISG15 transcription induced by UV-HCMV infection might be gradually decreased due to the termination of the IFN signaling through several negative regulatory mechanisms." (PMID 27564865, 2016). "In addition to IE1, the presence of additional viral functions that downregulate protein ISGylation was prompted by our observation that UV-HCMV infection resulted in a higher level of ISG15 conjugates than IE1-deleted mutant virus at late times." (PMID 27564865, 2016). "Since HCMV IE1 inhibits the activation of ISRE-containing promoters by sequestering STAT2 and PML, IE1 expression may be responsible for the suppression of free ISG15 and ISG15 conjugate levels during HCMV infection." (PMID 27564865, 2016). "Whilst the mechanisms by which ISG15 regulates CMV infection are currently unknown, it appears to possess antiviral activity as blocking ISG15 accumulation enhances viral replication and HCMV antagonizes both the production of unconjugated ISG15 and ISGylation." (PMID 31921100, 2019). "Therefore, we also investigated whether UL26 is covalently conjugated by ISG15 during HCMV infection." (PMID 27564865, 2016). "Among these candidates, five host factors (PML, Sp100, ISG15, IRP9, and RSAD2) have been related to HCMV infection and were further investigated." (PMID 37058447, 2023). "HCMV infection led to a moderate induction of MX1, IFIT3, and ISG15, compared to the mock infected cells, as expected." (PMID 37376632, 2023). "PARPi treatment in parallel with HCMV infection further increased the transcription of IFN-β and ISG15." (PMID 36146855, 2022). "To date, much of the research into cytomegalovirus infection and its inhibition by HERC5 and ISG15 has focused on human cytomegalovirus (HCMV) protein antagonism." (PMID 34207696, 2021). "Quantification of ISG15 mRNA by qRT-PCR revealed significant IRF3-dependent, IFN signaling-independent upregulation during HCMV infection." (PMID 30871003, 2019). "Our analysis with UV-HCMV and IE1-deleted mutant virus demonstrates that ISGylation is induced by HCMV infection and that IE1 plays a central role in downregulating ISGylation by reducing ISG15 transcription." (PMID 27564865, 2016). "Although our results show that IE1 is largely responsible for the suppression of ISG15 transcription, it is notable that CR208 infection resulted in slightly lower levels of ISGylation compared to UV-HCMV infection (compare lanes 10 and 15)." (PMID 27564865, 2016). "In the context of the HCMV infection, Ashley and colleagues demonstrated that the promoters of several core IRGs, including IFIT1, IFIT3, MX1, and ISG15, are transcriptionally induced by the activation of the transcription factor IRF3 and therefore function independent of the IFN responses." (PMID 36552792, 2022). "HCMV infection activates the transcription of IFN-β and ISG15." (PMID 36146855, 2022). "Studies of HCMV infection in the presence of cycloheximide (CHX) have shown upregulation of IFIT1 (IFI56), IFIT2 (ISG54), IFIT3 (cig49, ISG60), MxA (the protein produced from the Mx1 gene) and ISG15." (PMID 30871003, 2019).
HCMV infection (continued). "Induction of the IFN-independent ISG viperin during HCMV infection is known to be induced by either IRF3 or IRF1, binding directly to its promoter, and this may also be the mechanism of IFIT1, IFIT2, IFIT3, CXCL10, Mx1, Mx2 and ISG15 upregulation." (PMID 30871003, 2019). "Taken together, these results suggest that the initial antiviral innate immune response, to HCMV infection in cord-blood and adult peripheral derived DCs, is dominated by a strong IFN and pro-inflammatory cytokine signaling, and chemokine receptor binding, centered on the activation of ISG15." (PMID 28993767, 2017). "Although reduction of protein ISGylation during HCMV infection may be largely attributed to suppression of ISG15 transcription by IE1, it cannot be ruled out that IE1 also affects the ISGylation reaction." (PMID 27564865, 2016). "In addition, no detectable ISG15 protein expression was observed following HCMV infection in IRF3 knockdown CRISPR/Cas-9 clones indicating that IFN-independent control of ISG expression during HCMV infection of human fibroblasts is absolutely dependent on IRF3 expression." (PMID 30871003, 2019).
colon cancer (12 papers, 2013 to 2025). "For colon cancer patients, high levels of ISG15 are associated with poor prognosis." (PMID 39456585, 2024). "The therapeutic benefits of cocoa consumption and colon cancer risk could be featured with regulatory modulations of ISG15, MX1, and STAT as the central tumor suppressor genes in the protein-protein interaction network." (PMID 30949322, 2019). "In CRC tissues, ISG15, a ubiquitin-like molecule, is present at high levels and promotes the migration and proliferation of colon cancer cells; silencing of this protein results in decreased cell proliferation and metastasis." (PMID 39456585, 2024). "Here, we provide an acute example of this phenomenon, whereby the early expression of USP18, post-interferon treatment of HCT116 colon cancer cells is sufficient to fully suppress the expression of the ISG15 E1 enzyme, UBA7." (PMID 37756534, 2023). "Upregulation of ISG15 expression promotes colon cancer proliferation and metastasis, and when ISG15 is knocked down, there is an opposite effect." (PMID 35267998, 2022). "However, the mechanism by which AIM2 stimulates ISG15 expression in the absence of type I IFNs and the downstream effects of AIM2-induced ISG15 expression and ISGylation in colon cancer cells are unclear." (PMID 27626310, 2016). "Here we show that 5-FU and oxaliplatin induce DNA damage and activate cGAS/STING signaling leading to elevated expression of IFNβ, ISG15 and CXCL10 in mouse and human colon cancer cells as well as increased intratumoral CD8+ T cells in mice." (PMID 39469633, 2024). "By comparing the transcriptomic profile of colon cancer-cocultured MCs versus control MCs, we identified a number of deregulated genes, such as MMP-2, VEGF-A, PDGF-A, COX2, NOTCH1 and ISG15, which contribute to the enrichment of cancer-related pathways." (PMID 30987352, 2019). "Secreted LGALS3BP can inhibit colon cancer progression through binding to CD9/CD82, which suppresses Wnt/beta-catenin signaling via an ISG15-dependent proteasomal-ubiquitination mechanism." (PMID 27626310, 2016). "Furthermore, knockout of STING1 in HT29 human colon cancer cells significantly attenuated 5-FU plus oxaliplatin-induced levels of P-STING and expression of ISG15 and IFNβ." (PMID 39469633, 2024). "ISG15 is upregulated following trametinib treatment in colon cancer cells and suppresses the anticancer effect of trametinib, suggesting combined targeting of ISG15 and mitogen-activated protein kinase kinase (MEK) as a promising therapeutic strategy for colon cancer treatment." (PMID 36319753, 2022).